TNF (tumor necrosis factor)
Diseases named in the same sentence as TNF in open-access papers (continued):
Sharing a sentence is not in itself a finding about the gene and the disease.
Obesity (continued). "Pro-inflammatory factors such as tumor necrosis factor-α (TNF-α), interleukin 6 (IL-6), interleukin 8 (IL-8), interleukin 18 (IL-18), interleukin 1β (IL-1β), or chemokine ligand 2 (CCL2) are also produced by WAT and are all increased in obesity." (PMID 38474344, 2024). "Higher activity levels were associated with lower levels of inflammatory markers, but the study also discovered that the correlation between activity levels and TNF-α became non-significant after intervening with obesity factors." (PMID 38933362, 2024). "Neither the pro-inflammatory factors TNF-α and IL-1β nor the secretome from patients with obesity (that is enriched in inflammatory mediators) exhibited an effect on the modulation of the NLRP6 inflammasome in the human enterocyte cell line CCL-241." (PMID 38315242, 2024). "Obesity often correlates with heightened levels of systemic pro-inflammatory markers like C-reactive protein, TNF-α, TGF-β, leptin, and IL-6, and we have shown that reducing TNF-α and TGF-β1 levels improved AHR and fibrosis in the same HFD-induced obesity model." (PMID 38762465, 2024). "The obesity-related increase in VAT is characterized by the accumulation of macrophages, which are predominantly polarized M1 state and hence produce proinflammatory cytokines, including interleukin (IL)-1β, IL-6, and tumor necrosis factor-α (TNF-α)." (PMID 39201522, 2024). "The oral administration of Bifidobacterium longum NK49, Lactobacillus plantarum NK3, and Bifidobacterium longum PI10 improved obesity in mice by improving intestinal barrier integrity via glucagon-like peptide 1 (GLP1) and IL-10 induction, modulating immune cells, and lowering TNF-α expression." (PMID 38534735, 2024). "Molecular markers of inflammation, such as TNF-α, IL-6, and CRP, were significantly elevated in individuals with obesity and insulin resistance, and these markers could predict the development of T2DM." (PMID 40302954, 2024). "In addition to CRP, increased nitric oxide, tumor necrosis factor alpha (TNF-α), and IL-6 have been reported in women with overweight/obesity." (PMID 39236809, 2024). "In mothers without obesity, Flt3L, IL-6 and TNFα expression levels were comparable between those who gave birth at term and preterm." (PMID 39627409, 2024). "The results of the current study demonstrated the statistically significant increase of both basal and LPS-stimulated TNF-α secretion by cultured monocytes of participants with CHD and obesity, that indicates the pro-inflammatory activation of circulating monocytes in obese patients with CHD." (PMID 38572445, 2024). "Examination of the fibroinflammatory effects of obesity in MMP14LKO mice revealed that both WD and HFFC feeding in mice increased hepatic inflammatory marker gene expression—TNFα, CXCL2, CXCL9, TGFβ, and IL-1β—in WT mice, and this was attenuated in WD-fed MMP14LKO mice." (PMID 39282008, 2024). "In addition, obese skin, which is characterized by impaired barrier function, is more prone to inflammation than that of non-obesity, as ultraviolet B (UVB) irradiation increases the production of tumor necrosis factor-alpha (TNF-α), an inflammatory cytokine." (PMID 38953090, 2024). "Inflammatory cytokines, tumor necrosis factor-α (TNFα) and interleukin-6 (IL-6), both of which produce sleepiness and fatigue, are elevated in OSA and obesity, which might lead to extensive usage of CPAP therapy." (PMID 39162731, 2024). "Compared with the use of metformin, Qu (300 mg/kg), can assist metformin in reducing the levels of serum IL-6 and TNF-α, relieving the inflammatory response of obesity, and has good safety, with no obvious organ toxicity." (PMID 39712006, 2024). "As the present study was not conducted in mouse models of metabolic diseases such as obesity and diabetes, the main TNF-α-producing cells appeared to be immune cells, such as macrophages, other than inflammatory immune cells in adipose tissue." (PMID 39770998, 2024).
Obesity (continued). "SphK1 affects the migration and activation of inflammatory cells like macrophages and lymphocytes, as well as the production of cytokines including tumor necrosis factor-alpha (TNF-α), interleukin-6 (IL-6), and IL-10, thus serving both pro-inflammatory and anti-inflammatory functions in obesity." (PMID 39777222, 2024). "This review examines the major mechanisms between obesity and AD, which focus on the effect on skin and gut microbiota, immune responses mediated by the toll like receptor (TLR) signaling pathway, and changes in cytokine levels (TNF-a, IL-6, IL-4, and IL13)." (PMID 39564133, 2024). "Further elegant studies revealed that mice lacking TNF function exhibited improved insulin sensitivity and had lower levels of circulating free fatty acids in diet-induced obesity models." (PMID 38672492, 2024). "The aim of this study was to evaluate the association of changes in mitochondrial DNA copy number and violation of inflammatory response of circulating monocytes considered as excess secretion of inflammatory cytokine TNF-α in primary culture of monocytes obtained from patients with CHD and obesity." (PMID 38572445, 2024). "Our data represent a TNF-α/stearate cooperativity model driving IL-6 expression in 3T3-L1 cells via the H3K9/18Ac-dependent mechanism, with implications for adipose IL-6 exacerbations in obesity." (PMID 38928498, 2024). "In obesity, the release of FFA and cytokines (IL-6, IL-1β, PAI-1, TNF-α) from VAT into the portal vein may contribute to hepatic insulin resistance, hepatic triglyceride deposition, and NAFLD—the portal hypothesis." (PMID 39063184, 2024). "TNF-α was significantly elevated in MCR independent of sarcopenia but without obesity, while low IL-10 levels and IL-10/TNF-α ratio were associated with MCR, independent of sarcopenia and body composition." (PMID 38337499, 2024). "Higher levels of IL-1β (A, p < 0.0001), IL-6 (B, p < 0.0001), IP-10 (E, p < 0.001), GM-CSF (F, p < 0.0001), TNF-α (G, p < 0.0001), and IFN-γ (H, p < 0.0001), and lower IL-10 levels (I, p < 0.05) were found in the volunteers with obesity compared with the NW group." (PMID 39125408, 2024). "Seymour and co-workers reported, in obesity-prone rats fed with an HFD, that the intake of tart cherries reduced retroperitoneal IL-6 and TNF-α mRNA expression, Nuclear factor kappa B (NF-κB) activity, and plasma IL-6 and TNF-α concentrations." (PMID 38671836, 2024). "In patients with obesity with T2DM, liraglutide exerted anti-inflammatory effect by lessening TLR4, NF-κB and downregulating the expression of proinflammatory factors including TNF-α." (PMID 39133777, 2024). "In the group of patients with CHD and obesity, mtDNA copy number correlated with basal TNF-α secretion (R = 0.465, р = 0.001) as well as with LPS-stimulated secretion (R = 0.591, р<0.001), and TNF-α secretion after the second LPS-stimulation (R = 0.353, р = 0.024)." (PMID 38572445, 2024). "According to the multiple logistic regression analysis, the statistically significant variables that were associated with worse COVID-19 outcomes include female gender, obesity, pulmonary disease, chronic kidney disease, PDN ≥5 mg/day, and use of TNF-α inhibitors (95% CI, p < 0.05)." (PMID 39456932, 2024). "The levels of IFN-γ, IL-4 and IL-10 in two undernutrition infected groups were higher than those in normal + infection and obesity + infection groups, while the results of TNF-α and IL-12 p70 were not different among the groups." (PMID 38185681, 2024). "Adipocytes contribute to the secretion of proinflammatory cytokines such as TNF-α, IL-1β, MMP-2, MMP-9, IL-6, and MCP-1, as well as adipokines like adiponectin, which further contribute to chronic inflammation in adipose tissue of individuals with obesity." (PMID 38495901, 2024).
Obesity (continued). "Abdominal obesity is considered to be an inflammatory state, and many inflammatory factors come from visceral adipose tissue, such as IL-6, TNF-α, C-reactive protein (CRP), leptin, etc., which may lead to obesity-related airway inflammation." (PMID 38926790, 2024). "Particularly, TNF-α, a pro-inflammatory cytokine, is secreted in large amounts by WAT, and its elevated levels are believed to play a significant role in the pathogenesis of insulin resistance in obesity." (PMID 37571394, 2023). "Plausibly, TNF-α itself could modulate IL10 upregulation by KBs, as suggested by studies reporting that IL-10 is up-regulated by TNF-a in vitro as well as in obesity both in humans and rodents." (PMID 37508009, 2023). "At the same time, zinc demonstrated potential anti-inflammatory effects through cytokine signaling pathways and the reduction of plasma levels of IL-6, TNF-α, and CRP, with a protective effect against chronic low-grade inflammation, which is found in obesity and MetS." (PMID 38140353, 2023). "We show altered systemic cytokine balance in mothers with obesity, adding to existing literature in the field describing increased prenatal TNFα in mothers with obesity compared to mothers without obesity." (PMID 38068816, 2023). "Higher levels of adipokines, such as leptin, and elevated production of inflammatory cytokines, like interleukin-6 (IL-6) and tumor necrosis factor-alpha (TNF-α), in the adipose tissue of people with obesity can contribute to chronic inflammation and insulin resistance." (PMID 38023258, 2023). "This is accompanied by elevated plasma levels of conventional pro-inflammatory markers such as interleukin (IL)-6, tumor necrosis factor (TNF)-α, and C-reactive protein as well as local inflammation in the skeletal muscle microvasculature of overweight and/or individuals with obesity." (PMID 36441492, 2023). "Obesity induces persisting low-grade inflammation because of increasing macrophage infiltration, which further activates immune cells to release proinflammatory cytokines (i.e., CRP, TNF-α, and IL-6) into the circulation." (PMID 37778442, 2023). "An increase in IL-1β, IL-18, TNF-α, inflammasome NLRP3 activation, astrogliosis, and BBB permeability in the brain areas involved in the control of the intake of food such as the LH and hippocampus are the hallmarks of obesity-induced neuroinflammation." (PMID 36674982, 2023). "TNF-α was significantly elevated in MCR and slow gait, but significant association was only seen in MCR participants, independent of sarcopenia but not obesity, defined by body fat percentage." (PMID 37371414, 2023). "Baseline results of pro-inflammatory biomarkers, including serum interleukin (IL)-6, serum and gingival crevicular fluid (GCF), tumor necrosis factor (TNF)-a, serum C-reactive protein (CRP)/hs-CRP, and serum and GCF resistin, were higher in obesity subjects than in normal weight subjects." (PMID 37798684, 2023). "However, significant decreases in serum TNF-α and CRP were observed after a 10-week lifestyle intervention conducted with 23 children and adolescents with obesity." (PMID 38063544, 2023). "IAA, has been reported to be produced by the flora from tryptophan metabolism and can alleviate inflammation related to alcoholic liver disease and obesity by directly or indirectly regulating the balance between proinflammatory and anti-inflammatory cytokines (TGF-β, TNF-α, IL-10, and IL-22)." (PMID 37495941, 2023). "The expression of obesity-related mediators (SphK1 and S1PR1) is enhanced in metastatic lesions of syngeneic and spontaneous breast tumor obese mice, along with elevated levels of TNF-α and IL-6." (PMID 36880535, 2023). "Many cytokines, particularly Th1-derived cytokines such as TNF-α, IFN-γ, IL-6, and IL-2, are increased when obesity is present, resulting in chronic low-grade inflammation that may predispose individuals to hypersensitive reactions." (PMID 36614274, 2023).
Obesity (continued). "In obesity, it has been reported that there are significant changes in the gut-immune cell composition, leading to metabolic inflammation and gut dysbiosis via upregulation of inflammatory mediators like TLR4, TNF, and NFkB." (PMID 37720534, 2023). "A meta-analysis has shown that obesity can alter serum levels of pro-inflammatory mediators (i.e., IL-6, CRP, TNF-a, resistin and leptin) in patients with periodontitis, while periodontitis can alter the levels of these mediators in patients with obesity, aggravating the inflammatory profile." (PMID 37798684, 2023). "TLR-4 activation stimulates JNK, which, in turn, promotes the production of cytokines, including interleukin (IL)-1, interleukin (IL)-6, tumor necrosis factor (TNF)-a, chemokines, and other proinflammatory compounds (Hypothalamic Inflammation and Gliosis in Obesity)." (PMID 37764744, 2023). "Adipose tissue, the main executor of chronic inflammation in obesity, can secrete tumor necrosis factor (TNF‐α) and interleukin‐6 (IL‐6), which play a negative role in regulating the insulin signaling pathway, ultimately resulting in insulin resistance." (PMID 37823169, 2023). "This current systematic review and meta-analysis investigated the effect of dietary ALA on CVD risk factors, including inflammatory markers (CRP, IL-6, and TNF-α in serum), BP, and blood lipid profile (TG, TC, LDL cholesterol, and HDL cholesterol in serum) in patients with overweight or obesity." (PMID 37778442, 2023). "Interestingly, the expression of TNF-α and IFN-γ in circulating Vδ2 T cells further increased as the degree of obesity increased, and was also inversely correlated with serum 25(OH)D3 in T2D." (PMID 37908738, 2023). "TNF-α and hs-CRP are reliable markers for evaluating obesity-related chronic inflammation." (PMID 37582770, 2023). "Secondly, the expression of TNF-α and resistin increased in patients with SO compared to patients with normal body composition, with obesity and without sarcopenia, and with sarcopenia only." (PMID 37853348, 2023). "Although there are various studies showing that the efficacy of anti-TNF agents decreases in patients with obesity, no adverse outcomes were reported with rituximab treatment, similar to the presents study." (PMID 38813042, 2023). "Research has demonstrated that adipocytes’ secretion of TNF-α can prompt the phosphorylation of IRS-1 serine and reduce GLUT-4 expression, resulting in disruptions in insulin-regulated glucose metabolism and the onset of obesity-related IR." (PMID 38045856, 2023). "This influx of inflammatory immune cells into obese adipose tissue promotes the production of inflammatory cytokines such as tumor necrosis factor (TNF), interleukin-6 (IL-6), and interferon gamma (IFN-γ), which contribute to the chronic inflammatory state (metaflammation) observed in obesity." (PMID 37276236, 2023). "Apart from obesity increasing insulin, IGF-1, leptin, IL-6, TNF-α and decreasing levels of adiponectin which activates the PI3K-AKT signalling pathway in CRC, high BMI inhibits methylation of PI3K-AKT signalling pathway genes, constitutively activating the pathway." (PMID 37233716, 2023). "In a co-culture system using 3T3-L1 adipocytes and RAW264 macrophages, luteolin (20 μM) was found to inhibit JNK activation and block proinflammatory factor expression (TNF-α, MCP-1 and NO), thereby playing a major role in the regulation of adipose tissue inflammation and IR in obesity." (PMID 37036026, 2023). "The main objective of this study was to verify the effects of weight loss induced by RYGB on the circulating levels of systemic inflammatory markers adiponectin, resistin, leptin, TNF-alpha, IL1-beta interleukins, IL-6, IL-8, IL-17, IL-23 and IGF-1 in women with severe obesity and MS." (PMID 36788619, 2023).
Obesity (continued). "In obesity, proinflammatory T-helper 1 cells and classically activated macrophages (M1) are activated and produce various inflammatory cytokines, such as IFN-γ, tumor necrosis factor-α, and interleukin-1257,58." (PMID 36609599, 2023). "In metabolically unhealthy obesity (MUO), cytokine profile changes include an increase in pro-inflammatory markers like IL-6, TNF-α, MCP-1 and high-sensitivity C-reactive protein (hs-CRP) with a concomitant decrease in anti-inflammatory markers like adiponectin." (PMID 37081489, 2023). "By reducing TNF-α expression, CGWE may improve insulin sensitivity and reduce lipolysis, contributing to its anti-obesity effects." (PMID 37571229, 2023). "TNF-α is both an adipokine and a chronic inflammatory factor that has been proven to be involved in the pathologic process of PCOS and is a potential agent in obesity and androgen expression." (PMID 37427330, 2023). "Therefore, the aim of our study was to assess the relationship between selected measures of obesity (BMI, WC, RFM, VAI, WHtR) and parameters of chronic inflammation (CRP, TNF-α, IL-6) in perimenopausal women." (PMID 37375693, 2023). "Based on data from animal studies or other clinical applications in addition to obesity, adipokines including adiponectin, vaspin, resistin, chemerin, visfatin, bone morphogenetic protein 7 (BMP-7) and tumor necrosis factor alpha (TNF-α) provide potential for human clinical application." (PMID 37239098, 2023). "The anti-obesity and anti-inflammatory actions of TPDM6315 in TNF-α induced adipocytes suggest that this herbal recipe could be useful for the treatment of metabolic syndrome disorders caused by obesity." (PMID 37367060, 2023). "There are different PAI-1 inducers that can elevate the levels of PAI-1 during obesity such as transforming growth factor (TGF-β), pro-inflammatory mediators like TNF-α, hypoxia-inducible factor (HIF-1α), oxidative stress and dysregulation of the circadian clock." (PMID 37372025, 2023). "In addition, secretion of pro-inflammatory cytokines (TNF-α, IL-6, and CCL2) from macrophages and adipocytes is promoted in obesity, which is considered a form of chronic inflammatory disease." (PMID 34949748, 2022). "Unfortunately, the evidence on the effect of obesity on IBD anti-TNF therapy is currently conflictive and non-conclusive." (PMID 36687448, 2022). "TNF-α is a proinflammatory cytokine expressed in adipose tissue that might link obesity and IR and increases plasma FFA levels in obesity and T2DM." (PMID 36176469, 2022). "Accordingly, in this study, we observed elevated serum concentrations of TNF-α in CD-fed rats, indicating that TNF-α might mediate obesity-induced endothelial dysfunction." (PMID 35206342, 2022). "Interestingly, the link between Mtb infection and the immune response in adipose tissue has been evaluated and was found to affect the production of pro-inflammatory cytokines (TNF-α, IL-6, MCP-1) and leptin, which induces metabolic dysfunction in obesity." (PMID 35682832, 2022). "Tumor necrosis factor (TNF), which is mainly expressed and secreted by macrophages in the M1 state in adipose tissue, is one of the first cytokines found to be increased in adipose and circulating tissue in people with T2DM and obesity." (PMID 36648872, 2022). "Both groups including obese children showed higher leptin and IL-10 levels and lower adiponectin and TNF-alpha levels compared to children with no obesity and asthma." (PMID 36291398, 2022). "Obesity increases systemic levels as well as cellular secretion of many cytokines and adipokines including leptin, IL6, TNFα, IGF1, fatty acid binding protein 4 (FABP4), and resistin, which are all involved in regulating the pathways associated with the development of CSCs in breast cancer tissue." (PMID 36010901, 2022).